BRCA1 (BRCA1 DNA repair associated)
Diseases named in the same sentence as BRCA1 in open-access papers (continued):
Sharing a sentence is not in itself a finding about the gene and the disease.
tumor (continued). "A comparable example of an inhibitor interacting with PRC2 was recently described, in which the tumor suppressor BRCA1 interacts with PRC2 in mouse embryonic stem cells and inhibits PRC2 binding to genes involved in cell differentiation, promoting their expression." (PMID 26642436, 2015). "At least 3 scenarii can be elaborated: 1/BRCA1 mutation do not drive the oncogenesis of the tumor hence such a mutation would be considered as a “genetic incidentalom”." (PMID 26426992, 2015). "Finally, in Cal-27 cells with stable BRCA1 expression, we observed that the inhibition of tumor growth was attenuated by BRCA1 in response to cisplatin treatment while BRCA1 expression and miR-593-5p levels were increased." (PMID 25912308, 2015). "Our results indicated that germline truncation and missense variants in several genes were under selection in the tumour, with ATM, BRCA1, BRCA2 and RAD51C determined as significant from both truncation and missense analyses and BAP1, BRIP1, FANCM, PALB2 and RAD51D from truncation analysis alone." (PMID 26689913, 2015). "This study was the first to detect the prognostic roles and synergistic effects of JWA/XRCC1/BRCA1 mRNA expression in paraffin-embedded tumor tissues on molecular staging for personalized therapy of advanced ESCC who received cisplatin- or docetaxel-based treatments." (PMID 25925371, 2015). "Larger carrier series may be required to comprehensively evaluate associations by tumor subtype or, conversely, to establish that variation in HMMR interacts with Class I BRCA1 mutations to give rise to any type of tumor." (PMID 25830658, 2015). "By using multivariate Cox proportional hazards models with backward stepwise exclusion, XRCC1 (p = 0.002), FEN1 (p = 0.001), pol β (p = 0.032), BRCA1 (p = 0.040) and tumour stage (p < 0.0001) remained significant independent predictors for BCSS after controlling for adjuvant chemotherapy." (PMID 26267318, 2015). "BRCA1 is a critical tumour suppressor gene that possesses a PPRE within its promoter region." (PMID 25889730, 2015). "In addition, the percentage of miR-578, miR-573 and miR-122 overexpression in BRCA1/2 carriers and BRCAX associated tumors was also explored using the tumor mean level as cut-off." (PMID 25333258, 2015). "2/BRCA1 mutation triggers the initiation of the tumor but then does not control the tumor, this last been autonomous." (PMID 26426992, 2015). "However, it is possible that the BRCA1 mutant tumor would shrink and respond to olaparib, perhaps through a different and yet unrealized mechanism." (PMID 25984718, 2015). "We were unable to identify the precise reason for BRCA1 translocation; however it may be related to tumor re-growth." (PMID 25774336, 2015). "Here we show that human mammary epithelial cells (HMECs) from BRCA1-mutation carriers (BRCA1mut/+) exhibit increased genomic instability and rapid telomere erosion in the absence of tumour-suppressor loss." (PMID 26106036, 2015). "Although speculative, this list could include other key HDR genes including ATM, BRCA1/2, MRE11, RAD50, NBS1 or RAD51, which are also mutated in CRC and many other tumor types." (PMID 26318585, 2015). "BRCA1 and RAD17 mutations are rarely detected in sporadic tumours." (PMID 25650659, 2015). "BRCA1 mutation-positive cases were found among the serous, endometrioid and mixed cell subtype adenocarcinomas in contrast to BRCA2 mutation carriers, which were exclusively found among the serous subtype tumours." (PMID 25884701, 2015). "BRCA1 is a tumor suppressor that regulates DNA damage response." (PMID 25970777, 2015). "In turn, low abundance of BRCA1 would increase the genomic instability, increase the proliferation and decrease the differentiation of the tumor cells, all contributing factors to the malignant phenotype of a tumor." (PMID 25762631, 2015). "There would be no linkage between BRCA1 mutation and the tumor and the tumor can be considered as a sporadic tumor." (PMID 26426992, 2015).
tumor (continued). "Subsequent work has shown that, in addition to BRCA1/BRCA2 mutations, BRCA-like tumours may also have implications for PARPi-based therapy." (PMID 26610585, 2015). "It has previously been shown that the presence of a BRCA1 germline mutation and BRCA1 PM typically do not co-exist in the same tumor (i.e., BRCA1 PM is not observed in BRCA1 germline mutation associated tumors)." (PMID 25177489, 2014). "We noticed over-expression of this complex in BRCA1 compared to BRCA2 tumours." (PMID 25521701, 2014). "Deregulation of these miRNAs in TNBC may contribute to altered BRCA1 signalling and could partly explain the similarities of these tumours with those in which BRCA1 function is lost." (PMID 24479446, 2014). "ATR deficiency was significantly associated with menopause (P = 0.025), strong expression of ATM (P = 0.017) and MRE11 (P = 0.040) with pre-menopausal SOC, strong expression of MRE11 (P = 0.016) with low tumor grade, and strong expression of BRCA1 (P = 0.015) with early clinical stage." (PMID 24752797, 2014). "Open reading frame variants in BRCA1 have not clearly been associated with unique tumor biology, but only have been predictive of response to therapeutic agents that take advantage of their inherent DNA repair defects." (PMID 24915755, 2014). "Like BRCA1, Tax is also a multifunctional protein that interacts with multiple regulatory proteins and modulate their expression or functional activities, but while BRCA1acts as a tumor suppressor, Tax is a potent oncoprotein." (PMID 24586743, 2014). "Many of the PARPi currently under evaluation have been shown previously to have preferential cytotoxic activity for tumor cells with mutated or non-functional BRCA1 or BRCA2." (PMID 24970803, 2014). "A major finding was downregulation of glycolysis in BRCA1-expressing tumor cells." (PMID 25010005, 2014). "From this processes, BRCA1 role in DNA repair have gained special attention, as it might explains better the BRCA1 role in tumor suppression." (PMID 25594033, 2014). "Tumor suppressor functions of BRCA1 have been studied in mouse models." (PMID 24704793, 2014). "BRCA1 and TS mRNA expression was successfully assessed in tumor tissues from all 150 patients." (PMID 25496700, 2014). "In addition, the requirement for WRN in ALT is associated with an ALT-specific interaction between WRN and the BRCA1 tumor suppressor." (PMID 24709898, 2014). "This suggests that a mutation in BRCA1 could remove AKT inhibition and thus cause glycolysis to be up-regulated, eventually enabling tumor transformation." (PMID 25010005, 2014). "However, as demonstrated from the multitude of clinical studies, quantitative analysis of RRM1, ERCC1, and BRCA1 mRNA expression levels has been performed mainly on tumor specimens obtained from fiberoptic bronchoscopy biopsy or surgical resection." (PMID 24591771, 2014). "This hypothesis was strengthened by the fact that some of these BRCA1-like tumours showed BRCA1-promoter methylation." (PMID 25083859, 2014). "The presence of germline mutations provides a potential source to identify genetic targets for early intervention of tumorogenesis process in BRCA1+ carriers long before tumor formation in breast cells, for which there are currently limited options besides preventive surgery." (PMID 24884718, 2014). "This new global function in metabolism could represent another mechanism by which BRCA1 exerts its tumor suppressive function." (PMID 25010005, 2014). "Our study thus provided evidence of implication of BRCA1 in the regulation of bioenergetic metabolism, another mechanism by which BRCA1 may exert its tumor suppressor function." (PMID 25010005, 2014). "In this context, it is tempting to speculate that the tumor suppressor genes BRCA1 and BRCA2, as well as other factors that control the amount of ssDNA/RPA, might protect against HR-mediated genetic instability by regulating the formation of repair centers." (PMID 24615940, 2014).
tumor (continued). "In addition, the frequency of BRCA1 methylation was observed to be higher in the patients whose tumor was bilateral than that of patients whose tumor unilateral (P=0.015, Pearson’s χ2 test)." (PMID 24944674, 2014). "Pparγ has been shown to promote the transcription of tumor-suppressor genes like Pten and Brca1." (PMID 25176219, 2014). "Supporting that this finding is due to tumor biology, and not difficulty screening, obese women with the BRCA1-3’UTR-variant had significantly less dense breasts (p = 0.0398) in the Vermont cohort." (PMID 24915755, 2014). "Since oxidative stress causes carcinogenesis through genomic instability by way of DNA-damage and uncontrolled cell proliferation, regulation of the oxidative stress response by BRCA1 may constitute a wheel of the chariot of the BRCA1 tumor suppression." (PMID 24704793, 2014). "For example, a patient with a high-grade ER-negative tumor is three- to fourfold more likely to carry a BRCA1 mutation than not, whereas a patient with a low-grade ER-positive tumor is about 10 times more likely to be mutation-negative than mutation-positive." (PMID 25857409, 2014). "BRCA1 mRNA levels were successfully assessed in all 40 tumor samples, in 32 paired blood samples, and in 10 panels of mouse models, while TS mRNA levels were successfully assessed in all 40 tumor samples, all 40 blood samples, and in 9 panels of mouse models." (PMID 25496700, 2014). "The lack of functional BRCA (mainly, BRCA1) can lead to increased sensitivity of the tumor cells to molecular damage, demonstrating that BRCA mutations represent a predictive marker of response to DNA-damaging chemotherapies." (PMID 25253066, 2014). "A subclass of tumours in C showed copy-number alterations in cell cycle regulation and DDR pathways attributable to amplification of the gene encoding the mitotic regulator AURKA kinase and the inactivation of BRCA1 and BRCA2 genes." (PMID 24792170, 2014). "Influential TFs identified in pancreatic (normal vs PDAC) and breast (BRCA1 vs BRCA2) tumours." (PMID 25521701, 2014). "We assessed the efficacy of olaparib, cisplatin and their combination in the Brca1-deficient models after two weeks of treatment by measuring relative tumor volumes (RTV), the tumor volume changes from baseline (pre-dosing) to the end-point as determined by MRI." (PMID 24748377, 2014). "Notably, however, although BRCA1 is ubiquitously expressed in almost all tissues of the two genders, its tumor-suppressor functions are paradoxically oriented almost exclusively towards the female mammary and genital organs." (PMID 24586743, 2014). "Several functions of BRCA1 including roles in the DNA repair may contribute to its tumor suppressor activity." (PMID 25426449, 2014). "The PI3K/AKT pathway might have an essential role in the proliferation of malignant tumor cells related to the BRCA1 functions." (PMID 25426449, 2014). "PR expression in greater than 50% of tumor cells has been recently reported to have an overall survival benefit, and this benefit was independent of germline BRCA1/2 mutation status." (PMID 24478985, 2014). "Tumours may also acquire resistance by additional mutations in the BRCA1 & BRCA2 gene and so there is a place for further investigation of DNA repair inhibition in HR defective tumours." (PMID 25526776, 2014). "Furthermore, we showed by animal assays that the depletion of Aur A/B inhibited tumor growth of both cell lines, while the knockdown of BRCA1/2 promoted the tumor growth." (PMID 24775809, 2014). "Interestingly, the most enriched function is cellular maintenance, the function considered today as the major role of BRCA1 contributing to its tumour suppressor activity." (PMID 23805307, 2013).
tumor (continued). "In the case of BRCA1, women inherit one mutant allele and one wild-type allele; but in nearly all tumors that develop in BRCA1-mutation carriers, the wild-type allele is lost, leaving no functional BRCA1 in the tumor cells." (PMID 23802008, 2013). "However, they concluded that although MS110 did detect BRCA1 in FFPE tumor tissue samples, BRCA1 expression levels in standard methodologies were not reproducible enough to enable its use as a selection marker." (PMID 23855721, 2013). "Additionally, pre-clinical and clinical studies indicate that tumours with BRCA1 dysfunction are sensitive to platinum agents such as Cisplatin, and Carboplatin which function by causing DNA damage and promote tumour cell apoptosis." (PMID 25285241, 2013). "Only three of the 14 tumours with BRCA1 promoter hypermethylation had high 53BP1 protein levels." (PMID 24191908, 2013). "One of the important and well-studied proteins in the HR pathway is BRCA1, a tumor suppressor." (PMID 23388100, 2013). "As a rule, such a tumor develops at a young age (BRCA1-related, at 35–39 years old; BRCA2-related, at 43–54 years old) and characterized by hormone-independent growth, high rate of development in the opposite gland, high degree of malignancy, tendency to relapse, and worse prognosis." (PMID 24325835, 2013). "However, assuming that BRCA1 functions similarly in non-tumor cell types, the ability of BRCA1 to inhibit telomerase activity and cause telomere shortening are consistent with a tumor suppressor function." (PMID 23802008, 2013). "However, in the frozen sections, BRCA1 antibody staining showed punctate, intra-nuclear granules in varying numbers of tumor, lactating, and normal cells." (PMID 23855721, 2013). "This may reflect the fact that in our in-house data set, we were able to stratify BRCA1 mutant profiles based on triple negativity, and these tumours were therefore more likely to consistently display the ‘BRCAness’ phenotype." (PMID 23863842, 2013). "Moreover, EWS protein has also been described to interact with BARD1, a putative tumor suppressor component of the BRCA1/BARD1 complex that performs essential DNA repair and recombination functions." (PMID 24082883, 2013). "However, it is believed that the entire spectrum of BRCA1 activities remains to be discovered and that its tumor suppression function is yet to be defined." (PMID 24832651, 2013). "These considerations would suggest that the BRCA1: BARD1 interaction may have another ubiquitin ligase-independent function that is essential for tumor suppression." (PMID 23802008, 2013). "Because BRCA1 is a tumour suppressor, a number of mRNAs translationally regulated by a BRCA1-dependent mechanism may contribute to cell surveillance by encoding DNA repair factors, cell cycle and cell death regulators or transcription factors." (PMID 23805307, 2013). "A retrospective analysis of BRCA1 promoter methylation and 53BP1 protein levels in the patients enrolled in such trials could help confirm the predictive impact of this tumour profile." (PMID 24191908, 2013). "In addition, we have reported that significant correlation was found between expression of BRCA1 gene and degree of tumor as upregulated gene expression was related to the higher tumor grade." (PMID 24312913, 2013). "Thus, our findings uncover a key DSB repair role for RIF1 in 53BP1-dependent NHEJ, which has important ramifications for understanding DSB pathway choice and BRCA1’s tumor-suppressive functions." (PMID 23333305, 2013). "Finally, a recent paper reported that BRCA1 tumor suppression depends on BRCT phosphoprotein binding." (PMID 22646717, 2012).
tumor (continued). "The increased sensitivity of SUM149 was notable in that this model is BRCA1-deficient, suggesting that FK866 could also increase the sensitivity of HR-null tumour cells to PARP inhibition." (PMID 22933245, 2012). "Surprisingly, conventional null or hypomorphic Brca1 alleles revealed lack of tumor formation in heterozygous mice." (PMID 22347400, 2012). "Thus, we concluded that we have developed a BRCA1-IRIS specific monoclonal antibody that can be used in immunohistochemistry on paraffin-embedded tumor samples." (PMID 22511931, 2012). "However, the representation of carriers is different to that of familial FBC with direct comparison within the kConFab registry showing an increased proportion of BRCA2 male carriers and underrepresentation of BRCA1 male tumours." (PMID 23146383, 2012). "In addition, it has been reported that Smad3, a component of the transforming growth factor β (TGF-β) signaling pathway, which is a potent regulator of growth and apoptosis, also for invasiveness of tumor cells, forms a complex with BRCA1 in vitro and in vivo." (PMID 23203101, 2012). "Although it remains largely unknown how these complexes transmit BRCA1 signaling, it appears that these three complexes of BRCA1 are involved in multiple functions of BRCA1 and thus may be essential for BRCA1's tumor suppressor function." (PMID 22369660, 2012). "The most recent hypothesis on BRCA1 concerns a role in maintaining global heterochromatin integrity that might justify its tumor suppressor function." (PMID 22646717, 2012). "Together, BRCA1 emerges to be a central mediator of the cellular mechanism that maintains genome stability that brings together multiple signaling complexes in response to DNA damage, yet much remains to be learned to fully appreciate the role of BRCA1 as a tumor suppressor." (PMID 22369660, 2012). "Early embryonic lethality precluded tumor development in Brca1 (−/−) mice." (PMID 22347400, 2012). "In addition, there is evidence for a deletion/translocation phenotype potentially linked to germline BRCA1/2 mutations, with a high prevalence of small deletions being particularly marked in BRCA2 null tumours." (PMID 22514011, 2012). "The A, B and C complexes, at lease partially undertake BRCA1's role in mechanisms of cell cycle checkpoint and DNA repair that maintain genome stability, thus may play important roles in BRCA1's tumor suppressor function." (PMID 22369660, 2012). "Interestingly the Role of BRCA1 in DNA Damage and Response pathway was increased in both NB cells and tumor compared to ND cells." (PMID 22280838, 2012). "To test whether BRCA1-IRIS is a useful chemotherapeutic target for either of these tumor subtypes, we identified a cohort of HER2+ (n = 32) and a cohort of TN/BL (n = 72) tumors." (PMID 22511931, 2012). "The fact that the BRCT domains are frequently targeted by many clinically important mutations and most of these mutations disrupt the binding surface of the BRCT domains to phosphorylated peptides indicates that they are integral for BRCA1's tumor suppressor function." (PMID 22369660, 2012). "Although it is evident that BRCT domains are essential for BRCA1's tumor suppression, it remains unclear how the BRCT domain associated complexes are coordinated with signaling complexes that associate through other regions of the BRCA1 protein." (PMID 22369660, 2012). "Hence, the apparent differences in the strength of the SNP associations by BRCA1 and BRCA2 mutation status can be explained once tumour subtype is taken into account." (PMID 22053997, 2011).